TSPAN1 (tetraspanin 1)
Diseases named in the same sentence as TSPAN1 in open-access papers (continued):
Sharing a sentence is not in itself a finding about the gene and the disease.
tumor (continued). "Furthermore, the MTT assay showed that TSPAN1 depletion was able to inhibit the proliferation of ASPC-1 and PANC-1 cell lines and reduce the tumor growth of xenograft models silenced for TSPAN1 and implanted in nude mice." (PMID 36558998, 2022). "TSPAN1 is a novel member of the tetraspanin family, and its role in tumor progression is not entirely understood." (PMID 27556508, 2016). "Therefore, our results demonstrating that TSPAN1 is overexpressed in tumor tissues but not healthy tissues reveal a clear link with survival in PCC patients that are compatible with previous findings." (PMID 33188589, 2021).
cancer (36 papers, 2011 to 2025). A tumor composed of atypical neoplastic, often pleomorphic cells that invade other tissues. "TSPAN1 has been shown to cause cancer cell proliferation and angiogenesis by switching cell division signals and inducing differentiation or dedifferentiation of cells." (PMID 33188589, 2021). "Accordingly, TSPAN1 inhibition has been linked to decreased cell proliferation and apoptosis induction, as previously reported in other cancer types." (PMID 33167355, 2020). "Taken together, these studies suggest a positive role for TSPAN1 in cancer progression, but the mechanisms underlying this are currently poorly understood." (PMID 28701765, 2017). "The expression of TSPAN1 varies in different cancer types, making it a potential biomarker for cancer diagnosis and prognosis." (PMID 40777026, 2025). "TSPAN1, a tetraspanin family member, modulates cell surface protein trafficking and signaling, contributing to cancer cell proliferation and chemoresistance through pathways such as EGFR and integrin-mediated signaling." (PMID 39850570, 2024). "After forward search and backward search, we identified a set of five differentially expressed genes (LAMC2, TSPAN1, MYO1E, MYOF, SULF1) in Cancer/Normal that was optimized for diagnostic ability." (PMID 39850570, 2024). "The mRNAs most associated with TUCP_002240 are LYZ and TSPAN1; LYZ is a component of innate immunity, and TSPAN1 has a regulatory role in cancer." (PMID 36838374, 2023). "Meanwhile, we found that the expression of CA2 and TSPAN1 was significantly different between cancer tissues and normal tissues at protein level (all p < 0.05)." (PMID 34657172, 2022). "Tetraspanin 1 (TSPAN1) is highly expressed in several cancers and affects the progression of these tumors." (PMID 34852709, 2021). "Tetraspanin 1 (TSPAN1) is a cancer-related protein with a role in cell mitosis and leads to abnormal cell differentiation; TSPAN1 expression levels are significantly higher in patients with CRC than in healthy controls." (PMID 34685415, 2021). "One of the most upregulated protein, a member of the tetraspanin family, named TSPAN1, was primarily selected for its potential clinical interest in various cancer models." (PMID 33167355, 2020). "In silico analysis of TCGA database was performed to explore TSPAN1 mRNA expression more extensively in different cancer types." (PMID 33167355, 2020). "Because cancer-derived small-EVs are found in body fluids such as the plasma and serum, TSPAN1 can act as a small-EV biomarker for advanced CC diagnosis." (PMID 30382917, 2018). "Recent research studies on TSPAN1 have focused on its ability to promote proliferation and migration in cancers." (PMID 30514341, 2018). "By identifying a mechanism through which this protein can modulate cell migration this current study thus sheds new light on the role of TSPAN1 in cancer." (PMID 28701765, 2017). "As a member of the tetraspanin family, TSPAN1 has been reported to regulate cancer progression in many human cancers." (PMID 28701765, 2017). "It has been proposed that TSPAN1 gene expression correlates with cell proliferation and cancer prognosis." (PMID 22900095, 2012). "In fact, the effects of TSPAN1 on the progression of cancers have been widely revealed." (PMID 34852709, 2021). "Similarly, the region around the ISUP1 cancer in section 4 was annotated as benign but the model clustered it separately; it has high spatial expression of another migration-related gene TSPAN1." (PMID 34638322, 2021). "The fact that inhibition of TSPAN1 is able to sensitize resistant cells to different chemotherapeutic agents, has an important added value to be considered a potential novel target for cancer therapy." (PMID 33167355, 2020). "Recently, TSPAN1 was also reported as a cancer-related protein." (PMID 30382917, 2018). "In these studies, TSPAN1 was treated as an oncogene promoting cancer process." (PMID 30514341, 2018).
cancer (continued). "TSPAN1, TSPAN3, TSPAN12, TSPAN31, CD82 and CD63 have also been reported to reduce chemosensitivity of cancer cells." (PMID 36941633, 2023). "The following TSPANs have been involved in enhancing cancer therapy resistance: CD9, CD81, TSPAN1, TSPAN3, TSPAN31, CD82 and CD63." (PMID 36941633, 2023). "Based on the available evidence, CD81 and CD82, and TSPAN6 can serve as cancer suppressors, while CD151, TSPAN1, and TSPAN8 act as cancer promoters in the diagnosis and prognosis of HCC patients." (PMID 34540692, 2021). "Numerous studies have demonstrated that tetraspanin 1 (TSPAN1), a transmembrane protein, functions as an oncoprotein in many cancer types." (PMID 30514341, 2018). "Altogether, TSPAN1, TSPAN15, TSPAN29, and CD151 could support cancer cell growth, while TSPAN31, TSPAN6, CD9, CD37 could inhibit cancer growth." (PMID 36941633, 2023). "Considering the role of TSPAN1 in HCC cell proliferation, this gene therapy method can efficiently deliver the genes to cancer cells, which may be one kind of important precision treatment for HCC in the future." (PMID 34540692, 2021).
digestive system cancer (1 paper, 2024). A primary or metastatic malignant neoplasm involving any part of the digestive system. "Generally, the expression of CD9, CD151, Tspan1, Tspan5, Tspan8, Tspan12, Tspan15, and Tspan31 are upregulated, facilitating the migration and invasion of digestive system cancer cells." (PMID 38389703, 2024).
TSPAN1 also shares sentences with these, for which no sentence is quoted: liver cancer (2 papers); pancreatic ductal adenocarcinoma (2); acute myeloid leukemia (1); adenocarcinoma (1); adenoma (1); bacterial infections (1); cervical intraepithelial neoplasia (1); cervical squamous cell carcinoma (1); colorectal adenocarcinoma (1); glioma (1); head and neck cancer (1); infection (1); laryngeal carcinoma (1); Lymph node (1); melanoma (1); ovarian clear cell cancer (1); skin carcinoma (1); skin squamous cell carcinoma (1); squamous cell carcinoma (1).